SDR42E2 (short chain dehydrogenase/reductase family 42E, member 2)
Tractability: Small molecule: it belongs to a druggable protein family. PROTAC: ubiquitination databases record sites on it.
Gene: Protein-coding gene on chromosome 16 (22,162,492 to 22,192,208, forward strand). Ensembl gene ENSG00000183921.
Gene Ontology:
Molecular function: oxidoreductase activity, acting on the CH-OH group of donors, NAD or NADP as acceptor
Biological process: steroid biosynthetic process
Homologues: Orthologues: chimpanzee SDR42E2 (99% identical), macaque SDR42E2 (95% identical), dog SDR42E2 (89% identical), rabbit SDR42E2 (89% identical), pig SDR42E2 (86% identical), guinea pig SDR42E2 (86% identical), mouse Sdr42e2 (84% identical), rat Sdr42e2 (82% identical), tropical clawed frog sdr42e2 (53% identical), zebrafish sdr42e2 (53% identical), Caenorhabditis elegans hsd-2 (26% identical), Caenorhabditis elegans hsd-3 (23% identical). Paralogues in human: SDR42E1 (44% identical), HSD3B1 (25% identical), HSD3B7 (25% identical), HSD3B2 (24% identical), NSDHL (24% identical), GALE (18% identical), UXS1 (18% identical), TGDS (17% identical), GMDS (15% identical), GFUS (12% identical).